ALB (albumin)
Diseases named in the same sentence as ALB in open-access papers (continued):
Sharing a sentence is not in itself a finding about the gene and the disease.
malnutrition (continued). "The present study reported for the first time that preoperative malnutrition, based on albumin level and BMI, is associated with postoperative outcomes and short-time prognosis of the patients who underwent hepatectomy for CRLM, although the mechanisms remain largely unknown." (PMID 40225113, 2025). "MNA and SARC-F scales, combined with routine screening of elderly patients with frailty, may allow for effective identification of patients at risk of malnutrition and sarcopenia and with reduced albumin concentrations, which additionally worsens the prognosis." (PMID 40944175, 2025). "Furthermore, a screening nutritional assessment based on the MUST (Malnutrition Universal Screening Tool) would be conducted to stratify patients according to their preoperative malnutrition risk, and their preoperative albumin levels would be reported as well." (PMID 40870504, 2025). "Serum albumin is responsible for the maintenance of oncotic pressure and transport of coagulation factors, and a decrease in serum albumin levels may be associated with malnutrition and impaired hepatic synthetic function, which can lead to increased bleeding tendency." (PMID 41515598, 2025). "Both are closely associated with nutritional status: serum albumin reflects protein-energy malnutrition, as hepatic albumin synthesis depends on adequate protein intake, while lymphocyte levels are indicative of immune function, which can be impaired by malnutrition." (PMID 39964992, 2025). "Importantly, inflammation could result in malnutrition, evident by a reduction in albumin and weight loss." (PMID 38699426, 2024). "Hence, low serum albumin levels may indicate compromised nutritional status in the body, often associated with malnutrition or chronic diseases." (PMID 38745951, 2024). "Thus, the alterations in cholesterol and albumin levels might also be associated with an increased risk of developing malnutrition and aging symptoms." (PMID 39692768, 2024). "Despite the strong association of UA and ALB levels with cardiovascular diseases, supported by previous scientific evidence, there exist some controversies regarding the factors that affect UA and ALB concentration such as malnutrition, insulin, gout, diet, renal diseases, and metabolic syndrome." (PMID 38269629, 2024). "However, reduced albumin levels are typically associated with malnutrition and inflammatory conditions, triggering a cascade of detrimental effects, including increased oxidative stress, enhanced platelet activation and aggregation, and elevated thrombotic risk." (PMID 39474370, 2024). "However, clinical conditions other than liver deterioration may limit the predictive ability of the ALBI score, such as biliary obstruction, hemolysis, malnutrition and excessive albumin loss." (PMID 39421189, 2024). "In addition, it was observed in the results of the present study that adequate albumin level is essential for the prevention of postoperative complications in the elderly as hypoalbuminemia which represents the malnutrition state of the body, was linked with postoperative AHF significantly." (PMID 38800267, 2024). "Therefore, this correlation helps to recommend health professionals should preferentially focus on serum albumin and Hgb as alternative diagnostic modality for prompt identification of malnutrition before sign and symptoms manifest and to monitor adult patients with cancer on treatment." (PMID 36869395, 2023). "In addition, low levels of serum ALB may result due to inflammatory response and malnutrition; it also increases the susceptibility of patients to infection." (PMID 37790129, 2023). "Previous studies have proposed various hypotheses for the increase in cancer risk caused by low albumin concentration, including malnutrition due to neoplasm proliferation, antioxidant properties and inhibition of albumin synthesis due to systemic inflammation." (PMID 37836494, 2023).
malnutrition (continued). "The mechanism underlying the association between serum albumin levels and malnutrition in patients with HF may be related to the fact that serum total protein is primarily synthesized by the liver and has functions such as nutrition, buffering and maintenance of colloid osmotic pressure." (PMID 37034317, 2023). "In addition, patients with HF and anemia have several comorbidities, including CKD, malnutrition associated with cardiac cachexia, and a low albumin concentration, all of which may worsen the prognosis." (PMID 37540056, 2023). "Malnutrition can be referred to by following several different criteria, including more than 5% weight loss in three months or more than 10% in a six-month period, or a BMI less than 20 kg/m2, while albumin levels less than 35 g/L can be suggestive of malnutrition as well." (PMID 37111081, 2023). "Albumin is the main protein component in the total serum protein of normal human body, and its decline can be caused by long-term insufficient protein intake or increased consumption of patients caused by malnutrition and chronic consumptive diseases, especially for cancer patients." (PMID 37223117, 2023). "Low albumin in patients with heart failure is mainly manifested by reduced albumin synthesis and protein loss, which may be caused by hemodilution, chronic inflammatory states, hepatic congestion, malnutrition, cachexia due to volume overload, and proteinuria or intestinal disease." (PMID 36171266, 2022). "The authors concluded that 6 g of MCTs per day may significantly improve various blood parameters reflecting nutritional status, especially albumin, which is a risk indicator of malnutrition, compared to ingestion of LCTs in elderly people at risk of malnutrition." (PMID 35719157, 2022). "The reduction in ALP and ALB may be related to wasting and malnutrition caused by tumor burden." (PMID 36352168, 2022). "A cut-off point was defined at 3.1 g/dL so that patients with albumin values higher than or equal to that value are defined as having a low risk of malnutrition, and patients with values lower than that value are defined as patients with a high risk of malnutrition." (PMID 36558522, 2022). "Albumin is a negative acute-phase protein that decreases in concentration with ongoing systemic inflammation, poor health, and malnutrition which lead to the decreased skeletal muscle mass, hence, lower albumin might be associated with low-SMI value to reflect the sarcopenic condition." (PMID 35177018, 2022). "Critically ill patients were frequently observed with decreased serum albumin levels (SALs), which could result from redistribution of albumin between the vascular and interstitial spaces, nutritional deficiency, increased loss of albumin, and impaired hepatic albumin synthesis." (PMID 35769376, 2022). "Hypotheses for decreased albumin concentration with increased cancer risk raised by the previous study were varied from malnutrition, increased albumin consumption due to the expression of cancer cells, to antioxidant properties and inhibition of albumin synthesis caused by systemic inflammation." (PMID 34041866, 2021). "Therefore, we concluded that the highest quartile of NFI at diagnosis made a more direct contribution to predicting all-cause mortality through reduced serum albumin, which could reflect the high degree of inflammation and malnutrition." (PMID 33852653, 2021). "Strikingly, L3SMI and L3PMI were even independent from serum albumin concentration, which is an established marker of the nutrition state, highlighting that the effect of muscle loss on the patient ́s survival is complex and goes far beyond simple malnutrition." (PMID 34771524, 2021). "However, longer-term use of membranes with albumin leakage, such as with type V dialyzers, may still pose a risk of decreased serum albumin levels or malnutrition, and longitudinal studies are needed to evaluate this." (PMID 34112908, 2021).
malnutrition (continued). "Additionally, the initial value of serum albumin might also be a result of malnutrition and underlying disease that can worsen the nutritional status of the patient." (PMID 33397522, 2021). "While most nutritional risk index calculators utilize serum albumin to assess the nutritional status of patients, the mini nutritional assessment screening tool may be used to identify elderly people at risk of malnutrition prior to any decline in serum albumin levels." (PMID 33805128, 2021). "Besides this, preoperative serum albumin levels were determined as an independent risk factor for diminished postoperative activity and delayed recovery, correlating with the findings that malnutrition is a predictor for mortality after hip fractures and preoperative mobility for long term survival." (PMID 32411473, 2020). "Hence, the observed correlation between frailty and albumin deficiency could reflect a poor nutritional status in the studied population, suggesting that malnutrition is associated with higher frailty." (PMID 32306905, 2020). "Moreover, intestinal bleeding, malnutrition, and the loss of albumin may also contribute to the decrease in serum ChE levels in patients with IBD." (PMID 32733165, 2020). "The BMI (p < 0.001) and concentrations of albumin (p < 0.001), hemoglobin (p < 0.001), total cholesterol (p < 0.001), prealbumin (p < 0.001) and total protein (p < 0.05) among subjects at high risk of malnutrition assessed by MNA were significantly lower than those with low risk." (PMID 31159248, 2019). "Therefore, lower albumin level, as a marker of malnutrition and inflammation, could be a risk marker of CaC." (PMID 31138150, 2019). "Therefore, muscle mass or function (strength and performance) may decline as a result of degradation of protein synthesis caused by malnutrition, related to albumin levels." (PMID 31726780, 2019). "Moreover, the NMA detects the risk of malnutrition when albumin levels and BMI are still normal." (PMID 29628887, 2018). "Although protein loss from the gut and malnutrition may influence the serum albumin level, the albumin level is also known to decrease in active disease and to be negatively correlated with UC disease activity; this could explain the negative correlation between the serum albumin and FC levels." (PMID 29061121, 2017). "Serum albumin is also an indicator of diseases such as cancer, rheumatoid arthritis, and liver dysfunction and of underlying health conditions such as inflammation, frailty, low activities of daily living score, cognitive decline, and malnutrition in older adults." (PMID 27276092, 2016). "However, since serum albumin could decrease as kidney disease progresses as a consequence of anorexia and malnutrition, this association could be attributed to reverse causality." (PMID 15985177, 2005). "Low serum albumin levels were initially considered to result from protein malnutrition or “kwashiorkor-like” malnutrition, although the relationship between serum albumin and nutritional status remains controversial." (PMID 41550749, 2026). "Although the mechanisms by which these albumin-based composite markers of malnutrition influence clinical outcomes in patients with APE remain incompletely understood, several potential pathophysiological pathways have been proposed." (PMID 41608662, 2026). "Conversely, excessive inflammation suppresses albumin synthesis, perpetuating malnutrition and creating a self-reinforcing cycle that contributes to adverse outcomes." (PMID 41608662, 2026). "Occult malnutrition was defined by the coexistence of at least two abnormal biological markers: hypoalbuminemia (albumin < 3.5 g/dL), anemia (Hb < 12 g/dL), and elevated CRP (>0.5 mg/dL)." (PMID 41754103, 2026). "The malnutrition group had lower body weight, body mass index, hemoglobin, albumin, total lymphocyte count, and total protein, as well as higher C-reactive protein levels." (PMID 42152396, 2026).
malnutrition (continued). "These were a Pediatric End-Stage Liver Disease (PELD) score of ≥18, malnutrition, and lower preoperative fibrinogen, albumin, and hemoglobin levels." (PMID 42257075, 2026). "Concurrently, symptoms like chronic pelvic pain and anorexia contribute to malnutrition, further lowering albumin levels." (PMID 41601745, 2026). "Moreover, we did not have access to systematically recorded anthropometric or nutritional status variables (e.g., BMI, malnutrition/cachexia indicators), which may confound albumin-based associations and warrants dedicated investigation in future, prospectively phenotyped cohorts." (PMID 41598762, 2026). "A study from an LMIC estimated that 66% of children with WT had malnutrition, as determined by serum albumin and arm anthropometry." (PMID 40862782, 2025). "The low levels of serum albumin, which is synthesized by the liver, not only represents a state of malnutrition but also indicates a persistent systemic inflammatory response." (PMID 40881716, 2025). "ΔAlb in combination with GLIM-defined malnutrition would enhance the predictive value for postoperative outcomes in rectal cancer patients with normal preoperative albumin levels, and it is necessary to conduct a nutritional assessment for then." (PMID 40432957, 2025). "This suggests a less reliable or more context-dependent prognostic role for albumin in alcohol-related liver disease, potentially influenced by malnutrition or systemic inflammation." (PMID 40969799, 2025). "In HF patients, a low albumin level can indicate malnutrition, decreased liver synthesis, increased venous pressure, and visceral congestion." (PMID 40084147, 2025). "Nutritional status, as assessed by GNRI, integrates serum albumin and body weight, capturing both malnutrition and frailty, which are prevalent in elderly patients." (PMID 41085685, 2025). "ALB levels were similar, with malnutrition prevalent in 75.5% of Group A and 75.4% of Group B patients." (PMID 40313432, 2025). "Low serum albumin levels (p = 0.001), severe malnutrition with edema (p = 0.008), and need for blood transfusion (p = 0.001) were significantly associated with high mortality rate." (PMID 40981298, 2025). "Low albumin and high globulin levels reflect malnutrition and chronic inflammation, both of which are significantly associated with increased postoperative pain." (PMID 41018192, 2025). "TIBC, ferritin and albumin levels were markedly decreased in subjects with mild to moderate and severe malnutrition than well-nourished patients (P < 0.001)." (PMID 41327106, 2025). "In this study, we found that PD patients, particularly those in the malnutrition and sleep disturbances subgroups, exhibited lower albumin levels." (PMID 41551321, 2025). "Patients with Candida BSI typically presented with more advanced disease, more frequent palliative treatment, and indicators of poor functional status and malnutrition, notably lower serum albumin." (PMID 40175754, 2025). "In our patient, poor oral intake secondary to mucositis and advanced disease likely contributed to her malnutrition and low albumin levels." (PMID 41209896, 2025). "Changes inalbumin levels are indicative of systemic inflammation and nutritional status,low albumin levels, often reflecting either malnutrition or heightenedinflammatory responses." (PMID 40351679, 2025). "Decreases in hemoglobin and albumin are indicative not only of malnutrition in HD patients but also of a systemic inflammatory response." (PMID 39819254, 2025). "Decreased albumin levels are commonly observed in chronic inflammation and malnutrition, with low levels in liver damage potentially leading to immune dysfunction and worsening fatty liver progression." (PMID 40883838, 2025). "The CONUT score, by incorporating serum albumin, total cholesterol, and lymphocyte count, serves as a multidimensional index that reflects both malnutrition and systemic inflammation." (PMID 40722296, 2025).
malnutrition (continued). "No reductions were observed in laboratory parameters traditionally considered markers of malnutrition: serum albumin, prealbumin, and total cholesterol." (PMID 41515193, 2025). "Alternatively, interstitial albumin is also internalized by local cells and serves as a source of amino acids, e.g., in malnutrition." (PMID 40565207, 2025). "Low serum total cholesterol levels and albumin concentrations were important objective indicators of malnutrition." (PMID 40568584, 2025). "Standard laboratory tests for assessing malnutrition in senile patients include total lymphocyte count, albumin concentration, cholesterol level, hemoglobin level, transferrin level, and hematocrit." (PMID 40094974, 2025). "Decreased albumin levels often indicate malnutrition or metabolic disturbances secondary to chronic disease." (PMID 40725602, 2025). "ALB levels were similar, with malnutrition prevalent in both groups, although diabetic patients with malnutrition are correlated with lower VD levels." (PMID 40313432, 2025). "Protein-energy wasting (PEW) refers to a condition characterized by progressive malnutrition, which is marked by a decline in plasma albumin levels, excessive consumption of muscle proteins, a state of microinflammation, and in severe cases, cachexia." (PMID 40823296, 2025). "Malnutrition and cardiac cachexia, stemming from reduced appetite, gastrointestinal dysfunction, and increased metabolic demands, diminish hepatic albumin synthesis." (PMID 40703630, 2025). "One Croatian study suggested that hemoglobin level was correlated with Malnutrition Inflammation Score and serum albumin level in PD patients." (PMID 39944488, 2025). "Taken together, the high GPS, characterized by elevated CRP and low albumin levels, reflects significant systemic inflammation, malnutrition, and immune suppression." (PMID 40264786, 2025). "Albumin is also produced by the liver and is reduced in malnutrition, liver failure, and inflammation, and low levels are associated with frailty and cardiovascular disease." (PMID 40208300, 2025). "Malnutrition is highly prevalent in Polish dialysis patients and is linked with appetite impairment, elevated CRP, reduced albumin and poorer clinical status." (PMID 41159942, 2025). "In line with our findings, previous studies showed an inversely significant relationship between albumin levels and malnutrition in HD patients." (PMID 39854402, 2025). "Preoperative malnutrition was defined as a total lymphocyte count < 1,500 cells/mm3, a serum albumin concentration < 3.5 g/dL, or a transferrin concentration < 200 mg/dL within the six months before surgery." (PMID 40727701, 2025). "Primary outcomes were albumin (Nutritional marker used to assess malnutrition), CRP(C-reactive protein biomarker for systemic inflammation), IgA, interleukins, weight, quality of life, complications, and mortality." (PMID 41235306, 2025). "The CRP/Albumin ratio, as an indicator of systemic inflammation and malnutrition, proved to be a significant prognostic biomarker." (PMID 40797479, 2025). "Low albumin concentrations are associated with increased mortality, and advanced non‐small cell lung cancer patients often exhibit malnutrition, characterized by subnormal albumin levels." (PMID 39831739, 2025). "Malnutrition was prevalent in both groups, although decreased ALB levels in diabetic patients were correlated with reduced VD levels in comparison to diabetic patients with normal ALB levels." (PMID 40313432, 2025). "Studies characterized malnutrition as albumin <3.5 g/dL (n = 7) and total lymphocyte count <1500 (n = 1)." (PMID 40235527, 2025). "This study aims to explore the prognostic value of ΔAlb in combination with malnutrition for postoperative outcomes in rectal cancer patients with normal preoperative albumin levels." (PMID 40432957, 2025).